IL18RAP (interleukin 18 receptor accessory protein)
Description:
Within the IL18 receptor complex, does not mediate IL18-binding, but involved in IL18-dependent signal transduction, leading to NF-kappa-B and JNK activation. May play a role in IL18-mediated IFNG synthesis from T-helper 1 (Th1) cells (Probable).
Synonyms: IL-18RAcP; AcPL; IL-1RAcPL; IL-1R-7; IL-1R7; IL-18R-beta; IL-18Rbeta; CD218b; CDw218b; IL18RB
Tractability: Antibody: UniProt places it where antibodies can reach, with high confidence; its Gene Ontology location is reachable by antibodies, with high confidence; UniProt predicts a signal peptide or a membrane-spanning region. Other modalities: a drug acting on it is in phase 2 or 3 trials.
Gene: Protein-coding gene on chromosome 2 (102,418,570 to 102,452,567, forward strand). Ensembl gene ENSG00000115607.
Subcellular location: Cell membrane
Pathways (Reactome):
Immune System: Interleukin-18 signaling
Gene Ontology:
Molecular function: coreceptor activity; interleukin-18 receptor activity; protein binding; NAD+ nucleosidase activity, cyclic ADP-ribose generating; signaling receptor activity
Biological process: interleukin-18-mediated signaling pathway; cellular response to lipopolysaccharide; defense response to Gram-positive bacterium; immune response; inflammatory response; positive regulation of type II interferon production; T-helper 1 cell differentiation; cellular response to cytokine stimulus; cellular response to hydrogen peroxide; immune system process; signal transduction
Cellular component: interleukin-18 receptor complex; plasma membrane; cell surface
Genetic constraint (gnomAD): Loss-of-function variants: 37 observed, 58.04 expected, observed/expected ratio (o/e) 0.64, 90% interval 0.49 to 0.84. The upper end of that interval is the gene's LOEUF score, 0.84, which puts it in group 3 of 6, group 1 being the genes least tolerant of losing a copy. Missense variants: 651 observed, 714.61 expected, observed/expected ratio (o/e) 0.91, 90% interval 0.85 to 0.97. Synonymous variants: 255 observed, 263.15 expected, observed/expected ratio (o/e) 0.97, 90% interval 0.87 to 1.08.
Homologues: Orthologues: chimpanzee IL18RAP (98% identical), macaque IL18RAP (94% identical), pig IL18RAP (74% identical), dog IL18RAP (72% identical), rabbit IL18RAP (71% identical), rat Il18rap (66% identical), mouse Il18rap (65% identical), guinea pig IL18RAP (60% identical), tropical clawed frog il18rap (36% identical). Paralogues in human: IL1RAPL2 (28% identical), IL1RAPL1 (26% identical), IL18R1 (23% identical), IL1RL2 (22% identical), IL1RL1 (22% identical), IL1RAP (22% identical), IL1R1 (21% identical), SIGIRR (13% identical), IL1R2 (12% identical), LAG3 (12% identical).
Diseases named in the same sentence as IL18RAP in open-access papers:
IL18RAP is named in the same sentence as 97 diseases in open-access papers, as found by Europe PMC text mining. Sharing a sentence is not in itself a finding about the gene and the disease. The quoted sentences say what the papers report.
celiac disease (11 papers, 2009 to 2022). An autoimmune genetic disorder with an unknown pattern of inheritance that primarily affects the digestive tract. "Pertaining to inflammatory disorders, the rs917997 single nucleotide polymorphism (SNP) in IL18RAP was found to have a divergent role, conferring risk for celiac disease but protection for type I diabetes." (PMID 33919154, 2021). "This SNP is an eQTL for IL18RAP and celiac disease risk, with the minor disease-associated allele linked with reduced T-bet binding and IL18RAP gene expression." (PMID 28187197, 2017). "rs1465321 and rs2058622 are in high LD with SNPs associated with low expression of IL18RAP in celiac disease." (PMID 28187197, 2017). "The SNP rs917997 has previously been reported to be associated with differential expression of IL18RAP gene in coeliac disease patients." (PMID 23522322, 2013). "rs1465321 is in high LD with multiple SNPs associated with celiac disease, including rs13015714 and rs917997, identified as the strongest risk alleles for celiac disease in 2q12.1, with the disease-associated alleles linked to reduced IL18RAP expression." (PMID 28187197, 2017). "Interestingly, the IL18RAP gene was also recently shown to be associated with celiac disease, a chronic inflammatory disease of the small intestine with autoimmune features." (PMID 23634226, 2013). "Researchers have been studied that IBD and celiac disease have the similar genetic background; IL18RAP, PTPN2, TAGAP, and PUS10 have been identified as shared risk loci for both CD and celiac disease." (PMID 36204317, 2022). "Forty eight of our DE genes belong to this pathway, including 4 genes that have been genetically linked to coeliac disease: CCR1, IL18RAP, IL21 and IL2RA." (PMID 26444573, 2015). "A recent study, which included analysis of the Irish samples analysed in this study, has identified functional genetic variants at IL18RAP, a receptor for IL18, as a risk factor in coeliac disease." (PMID 20478055, 2010). "Noteworthy is that IL18RAP and CCR3, both recently identified as being genetically associated with celiac disease, exhibited significant cis-regulation in the celiac peripheral blood dataset but not in the HapMap B cell line dataset." (PMID 19128478, 2009). "Furthermore, we have identified genetic variants that alter T-bet binding to DNA, both in vitro and in vivo, including rs1465321, which we also identify as an eQTL for IL18RAP and celiac disease." (PMID 28187197, 2017). "Our finding that there are two independent eQTLs for IL18RAP, and that only one of these is associated with celiac disease, suggests that the level of IL18RAP expression may not be functionally relevant for disease susceptibility." (PMID 28187197, 2017). "In addition, tests for epistasis using Plink software did not suggest any interaction between these IL18 and IL18RAP genes in coeliac disease susceptibility." (PMID 20478055, 2010).
Crohn disease (8 papers, 2013 to 2025). A gastrointestinal disorder characterized by chronic inflammation involving all layers of the intestinal wall, noncaseating granulomas affecting the intestinal wall and regional lymph nodes, and transmural fibrosis. "The study also mentioned that this gene polymorphism was significantly associated with ulcerative colitis and Crohn’s disease, which indicated the pro-inflammatory role of IL18RAP in these inflammatory gastrointestinal morbidities." (PMID 35092558, 2022). "Of note, mutations in the IL-18 receptor accessory protein (IL18RAP) gene are associated with Crohn’s disease and IBD." (PMID 27148488, 2016). "A mutation of IL18RAP is closely related to both Crohn's disease and IBD." (PMID 31093495, 2019).
asthma (7 papers, 2015 to 2025). "Intriguingly, we newly discovered that the leading SNP in the IL18RAP locus showed concordant effects on the risk between leprosy and asthma." (PMID 38020709, 2023). "The concordant effect shows that the variant rs17027258 in the IL18RAP locus in leprosy shares a similar mechanism of Th2‐mediated responses in asthma." (PMID 38020709, 2023). "As another example, IL1RL1 pQTLs colocalised with IL1RL1, IL18R1 and IL18RAP eQTLs detected in multiple cell types with direct effects on the immune system (e.g. T-cells); these variants were associated with asthma and allergic reactions in the PheWAS." (PMID 38565889, 2024). "One of the most replicated asthma-associated genetic signals is the chromosome 2q12 locus, containing the IL-1 receptor like 1 (IL1RL1), IL18R1, and IL-18 receptor accessory protein (IL18RAP) genes." (PMID 32324168, 2020). "Among these targets, FPR1 (Formyl Peptide Receptor 1), IL1RAP (Interleukin 1 Receptor Accessory Protein), IL7R (Interleukin 7 Receptor), and IL18RAP (Interleukin 18 Receptor Accessory Protein) warrant additional exploration as potential therapeutic targets for AD and moderate to severe asthma." (PMID 40951943, 2025). "SMR results suggested that therapies targeting FPR1, IL1RAP, IL7R, and IL18RAP inflammatory variables may be able to prevent an increase in AD in moderate to severe asthma." (PMID 40951943, 2025).
Sepsis (7 papers, 2013 to 2025). Sepsis is defined as life-threatening organ dysfunction caused by a dysregulated host response to infection. "The qPCR results suggested that GK and PFKFB3 might contribute to the progression of S. aureus-induced sepsis, and GK, CEACAM1, TNFAIP6, PSTPIP2, SOCS3, and IL18RAP might be closely linked with E. coli-induced sepsis." (PMID 31093495, 2019). "The qPCR results suggest that GK and PFKFB3 might contribute to the progression of S. aureus-induced sepsis, and CEACAM1, TNFAIP6, PSTPIP2, SOCS3, and IL18RAP might be closely linked with E. coli-induced sepsis." (PMID 31093495, 2019). "We found evidence of sepsis eQTL that affected specific genes previously implicated in sepsis pathogenesis and treatment, including eQTL for IL18RAP, which encodes an accessory protein that enhances IL18-binding activity and is upregulated in patients with SRS1." (PMID 26917434, 2016). "In the genes differentially expressed between SRS groups, there was evidence of enrichment for eQTL (χ2 p<0·0001), including for genes previously implicated in the pathogenesis of sepsis and its treatment, such as IL18RAP, CCR1, CCR3, and SIRT1 (appendix 1 pp 17–18 and appendix 2)." (PMID 26917434, 2016). "Given that microRNAs embedded within protein coding genes are often co-regulated, we also assessed IL-18RAP mRNA expression as a potential biomarker of sepsis." (PMID 24146790, 2013). "IL-18 itself has previously been reported to be upregulated during sepsis and given its genomic location adjacent to IL18RAP, is likely to be co-ordinately regulated." (PMID 24146790, 2013). "In addition, the observed up-regulation of (counter-) receptors of interleukin-1 and -18 (IL1R2, IL18R, IL18RAP), still holds true when comparing patients with sepsis to healthy controls." (PMID 29920518, 2018). "Supporting the significance of the inflammasome in sepsis survivors, they also exhibited increased expression of genes downstream from inflammasome activation including interleukin-1 receptor 2 (IL1R2), IL18R1, and the IL-18 receptor accessory protein (IL18RAP)." (PMID 25538794, 2014).
inflammatory bowel disease (6 papers, 2013 to 2025). A spectrum of small and large bowel inflammatory diseases of unknown etiology. "Interestingly, IL18RAP polymorphisms have been associated with inflammatory bowel disease." (PMID 28241075, 2017). "The heatmap of molecules participate in the “inflammatory bowel disease” revealed higher expression of NF-κB1, IFN-γ, IL18, IL1B, and IL18RAP in Group AOSC than in Group CD-AOSC." (PMID 41438472, 2025). "The inflammatory bowel disease is highlighted (q-value = 0.015) through KEGG enrichment analysis using FABIO significant genes, and the involved genes are IL18RAP, IL4, GATA3, and SMAD3 (FABIO PIP = 1, 0.76, 1, and 0.75, respectively)." (PMID 39621803, 2024).
leprosy (5 papers, 2013 to 2023). Leprosy is a chronic infectious disease affecting primarily the skin and peripheral nervous system. "For example, the leprosy susceptibility allele of rs2058660 is associated with reduced IL18RAP expression in blood but increased expression of IL18R1 in the lung." (PMID 34879060, 2021). "The C allele is associated with low expression of IL18RAP, and according to the GWAS data, the ‘TT' genotype is linked with a higher incidence of leprosy, while ‘CC' is the risk genotype for IBD." (PMID 26259071, 2015). "However, rs2058660 is an eQTL for IL18RAP in neutrophils where the allele associated with leprosy risk (and CD protection) drives lower expression of IL18RAP, hence a more subdued pro-inflammatory signalling by IL18." (PMID 34879060, 2021). "In addition, IL18RAP and CYP27B1 were pinpointed as causal genes through colocalized the leprosy‐associated signals with eQTL signals of skin and nerve." (PMID 38020709, 2023). "At this stage of pathogenesis, blunted IL18 signalling in leprosy either by reduced IL18RAP expression or reduced IL18 binding by IL18R1 would hinder the development of anti-inflammatory host responses, which is expected to be beneficial for countering an infectious agent." (PMID 34879060, 2021). "The IL18R1 gene is clustered with IL18RAP and IL1RL1 in the leprosy GWAS locus on chromosome 2q12.1." (PMID 34879060, 2021).
type 1 diabetes (5 papers, 2021 to 2024). "Recently, GWAS have revealed that the IL18RAP-rs917997 is protective in type 1 diabetes but confers susceptibility to CeD12." (PMID 38716950, 2024). "Genetic variants in IL18RAP are associated with many immune-mediated diseases, including atopic dermatitis and type 1 diabetes." (PMID 34669738, 2021). "Genome-based approaches for identifying genetic polymorphisms associated with Type 1 diabetes (such as IL-2RA and CUX2) have revealed specific SNPs (such as PTPN22, IL-10, IL-27, and IL18RAP) with contrasting effects on the development of Type 1 diabetes." (PMID 38474087, 2024).
rheumatoid arthritis (4 papers, 2019 to 2023). A chronic, systemic autoimmune disorder characterized by inflammation in the synovial membranes and articular surfaces. "Not only affecting disease susceptibility, IL18RAP expression in synovial tissues was shown to associate with treatment response in rheumatoid arthritis patients." (PMID 33919154, 2021). "Our results suggest that IL18RAP expression is worthy of further investigation as a potential predictor of treatment response in rheumatoid arthritis that is not specific to a particular drug type." (PMID 32732242, 2020).
autoimmune disease (3 papers, 2019 to 2024). A disorder resulting from loss of function or tissue destruction of an organ or multiple organs, arising from humoral or cellular immune responses of the individual to their own tissue constituents. "IL18RAP is associated with a variety of autoimmune diseases including lupus, celiac, but especially with CAD via whole blood expression levels, and associated with MI via IL18 SNPs." (PMID 38978787, 2024). "Others were associated with autoimmune disease, such as systemic lupus erythematosus (SLE), ALS, and RA: CHIT1, IL18RAP, PHF24, and TPST1." (PMID 38978787, 2024).
lupus (3 papers, 2021 to 2024). "We therefore hypothesized that IL18RAP in neutrophils could be dysregulated in expression and function in lupus patients." (PMID 33919154, 2021).
Autoimmunity (2 papers, 2021 to 2024). The occurrence of an immune reaction against the organism's own cells or tissues. "The majority of studies on IL18RAP focus on genetic association analyses that encompass a diverse spectrum of conditions including cancer, cardiovascular disease, autoimmunity, and infections." (PMID 33919154, 2021).
esophageal carcinoma (2 papers, 2021 to 2023). A primary or metastatic malignant neoplasm involving the esophagus. "The IL18RAP polymorphism may be associated with malignant progression of esophageal carcinoma, suggesting that IL18RAP may have tissue specificity in different types of cancer." (PMID 34631695, 2021).
gastric cancer (2 papers, 2022). A primary or metastatic malignant neoplasm involving the stomach. "Another study found that individuals carrying IL18RAP single-nucleotide polymorphisms rs917997 were more vulnerable to gastric cancer or precancerous disease (odds ratio = 1.83)." (PMID 35092558, 2022).
glioma (2 papers, 2019 to 2023). A benign or malignant brain and spinal cord tumor that arises from glial cells (astrocytes, oligodendrocytes, ependymal cells). "Through the TISCH2 database, we identified the cell subtypes in LAML (GSE154109), glioma (GSE131928_10X), HNSC (GSE103322), OV (GSE130000), and PRAD (GSE150692) and described the IL18RAP expression levels in different clusters of cells." (PMID 37698530, 2023). "The remaining genes (IL-1α, CXCL7, IL-18RAP, CCL3) have not been well-studied in glioma, with the exception of CCL3, which is shown to improve the response to dendritic cell vaccines of patients with GBM." (PMID 31475119, 2019).
influenza (2 papers, 2014 to 2019). An acute viral infection of the respiratory tract, occurring in isolated cases, in epidemics, or in pandemics; it is caused by serologically different strains of viruses (influenzaviruses) designated A, B, and C, has a 3-day incubation period, and usually lasts for 3 to 10 days. "Published transcriptional profiles of NK cells, ILC1, and influenza-specific Id2-deficient mouse CD8+ T cells showed a striking concordance of Id2-dependent expression with our innateness gradient genes, highlighted by TBX21, ZEB2, IL18RAP, CCR7, TCF7, cytotoxicity, and KLR genes." (PMID 30737409, 2019).
viral infection (2 papers, 2022 to 2025). "While our study primarily focuses on transcriptomic data, in vivo evidence from other disease models supports the modulation of CXCR1 and IL18RAP genes during viral infections." (PMID 40124360, 2025). "It has been reported that genes related to cytotoxicity, such as Granzymes, NKG7, and IL18RAP, are upregulated in CD4+ CTLs in a mouse viral infection model, similar to what we saw in the present study, suggesting that these genes are generally induced in CD4+ CTLs upon viral infections." (PMID 36077655, 2022).
allergic conjunctivitis (1 paper, 2025). "Differential expression of Il18r1 and Il18rap in the allergic conjunctivitis mouse model conjunctiva (scRNA-seq)." (PMID 41476961, 2025).
amyotrophic lateral sclerosis (1 paper, 2024). Amyotrophic lateral sclerosis (ALS) is a neurodegenerative disease characterized by progressive muscular paralysis reflecting degeneration of motor neurons in the primary motor cortex, corticospinal tracts, brainstem and spinal cord. "While these results do not withstand statistical correction and warrant independent replication, they are complementing a recent study which identified a highly significant depletion of 3’UTR variants in the gene IL18RAP in amyotrophic lateral sclerosis (ALS) patients." (PMID 39715278, 2024).
atherosclerosis (1 paper, 2009). A disease characterized by the build-up of fatty material and calcium deposition in the arterial wall resulting in partial or complete occlusion of the arterial lumen. "IL18R1 and IL18RAP genes code for two receptors of the IL-18 cytokine that has been found associated with atherosclerosis and its cardiovascular complications." (PMID 19473509, 2009).
atopic asthma (1 paper, 2009). An asthma that is characterized by symptoms that are triggered by an allergic reaction caused by inhaled allergens such as dust mite allergen, pet dander, pollen and mold. "While IL18R1 and IL18RAP polymorphisms have been found associated with diseases such as schizophrenia, HSV1 seropositivity and atopic asthma, little is known about their contribution to CVD." (PMID 19473509, 2009).
bacteremia (1 paper, 2019). "IL18RAP is a subunit of the heterodimeric receptor for interleukin 18 and is reported to be elevated in E. coli-caused bacteremia." (PMID 31093495, 2019).
bacterial meningitis (1 paper, 2015). Inflammation of the membranes surrounding the brain and spinal cord due to a bacterial infection. "Most interestingly, these factors may positively (e.g., IL33 and IL18rap) and negatively contribute to regulation of NF-κB, which is a hallmark feature of bacterial meningitis." (PMID 25993608, 2015). "Most interestingly, these factors may positively (e.g., IL33 and IL18rap) and negatively (Tnfaip3, CISH and Zfp36) contribute to regulation of NF-κB, which is a hallmark feature of bacterial meningitis." (PMID 25993608, 2015).
Barrett esophagus (1 paper, 2021). Esophageal lesion lined with columnar metaplastic epithelium which is flat or villiform. "IL18RAP is a susceptible gene in esophageal adenocarcinoma and Barrett’s esophagus." (PMID 33955820, 2021).